PHC1 (polyhomeotic homolog 1)
Description:
Component of a Polycomb group (PcG) multiprotein PRC1-like complex, a complex class required to maintain the transcriptionally repressive state of many genes, including Hox genes, throughout development. PcG PRC1 complex acts via chromatin remodeling and modification of histones; it mediates monoubiquitination of histone H2A 'Lys-119', rendering chromatin heritably changed in its expressibility. Required for proper control of cellular levels of GMNN expression.
Synonyms: hPH1; EDR1; RAE28; MCPH11
Tractability: PROTAC: UniProt records ubiquitination sites on it; ubiquitination databases record sites on it; its protein half-life has been measured.
Gene: Protein-coding gene on chromosome 12 (8,913,827 to 8,942,938, forward strand). Ensembl gene ENSG00000111752.
Subcellular location: Nucleus
Subcellular location (Human Protein Atlas): Nucleoplasm; Mid piece
Pathways (Reactome):
Metabolism of proteins: SUMOylation of DNA damage response and repair proteins; SUMOylation of DNA methylation proteins; SUMOylation of RNA binding proteins; SUMOylation of chromatin organization proteins; SUMOylation of transcription cofactors
Gene expression (Transcription): RUNX1 interacts with co-factors whose precise effect on RUNX1 targets is not known; Transcriptional Regulation by E2F6
Cellular responses to stimuli: Oxidative Stress Induced Senescence
Developmental Biology: Differentiation of naive CD4+ T cells to T helper 2 cells (Th2 cells)
Signal Transduction: Regulation of PTEN gene transcription
Gene Ontology:
Molecular function: protein binding; chromatin binding; histone binding; zinc ion binding
Biological process: chromatin remodeling; heterochromatin formation; negative regulation of DNA-templated transcription
Cellular component: nucleoplasm; nucleus; PcG protein complex; PRC1 complex; chromatin; nuclear body; sex chromatin
Genetic constraint (gnomAD): Loss-of-function variants: 11 observed, 56.46 expected, observed/expected ratio (o/e) 0.19, 90% interval 0.12 to 0.32. The upper end of that interval is the gene's LOEUF score, 0.32, which puts it in group 1 of 6, group 1 being the genes least tolerant of losing a copy. Missense variants: 424 observed, 608.84 expected, observed/expected ratio (o/e) 0.7, 90% interval 0.64 to 0.75. Synonymous variants: 181 observed, 226.36 expected, observed/expected ratio (o/e) 0.8, 90% interval 0.71 to 0.9.
Homologues: Orthologues: chimpanzee PHC1 (99% identical), macaque PHC1 (99% identical), rabbit PHC1 (96% identical), dog PHC1 (95% identical), pig PHC1 (94% identical), guinea pig PHC1 (93% identical), rat Phc1 (93% identical), mouse Phc1 (93% identical), tropical clawed frog phc1 (56% identical), Drosophila melanogaster l(3)mbt (12% identical), Drosophila melanogaster Sfmbt (6% identical), Caenorhabditis elegans mbtr-1 (6% identical), and 1 more. Paralogues in human: PHC2 (30% identical), PHC3 (29% identical), SFMBT2 (11% identical), SFMBT1 (11% identical), L3MBTL3 (10% identical), SAMD11 (10% identical), SCMH1 (10% identical), L3MBTL4 (9% identical), SCML2 (9% identical), L3MBTL1 (9% identical), L3MBTL2 (7% identical), MBTD1 (7% identical), and 6 more.
Diseases named in the same sentence as PHC1 in open-access papers:
PHC1 is named in the same sentence as 25 diseases in open-access papers, as found by Europe PMC text mining. Sharing a sentence is not in itself a finding about the gene and the disease. The quoted sentences say what the papers report.
Primary microcephaly (4 papers, 2015 to 2023). Head circumference below 2 standard deviations below the mean for age and gender at birth. "Individuals with mutations in the PHC1 gene are described as having primary microcephaly or cerebral malformations that cause intellectual disabilities." (PMID 37771660, 2023). "A homozygous 2974C>T mutation in the PHC1 gene on chromosome 12p13 was reported in a 12-year-old girl and her 6-year-old brother born to related Saudi parents who were suffering from primary microcephaly." (PMID 25951892, 2015). "Regulates cell cycle, PHC1 mutation highlights the role of chromatin remodelling in the pathogenesis of Primary Microcephaly." (PMID 25951892, 2015).
microcephaly (3 papers, 2015 to 2020). A congenital or acquired developmental disorder in which the circumference of the head is smaller than normal for the person's age and sex. "PHC1 is associated with microcephaly and intellectual disability (DisGeNET)." (PMID 30710087, 2019). "Along with the chromatin regulators PHC1 (microcephaly) and KDM6A (Kabuki syndrome), another paradigmatic example is the ATP-dependent chromatin remodeler CHD8 (mSNC in enhancer), which controls neural progenitor cell proliferation through WNT-signaling related genes." (PMID 32299352, 2020). "Many genes have been implicated in the development of microcephaly (summarized inTable 1) includingASPM,MCPH1,CDK5RAP2,CEP152,CENPJ,WDR62,STIL,CASC5,CEP135,ZNF335,PHC1,CDK6, with many of them contributing to centrosome and spindle protein dysfunction during mitosis." (PMID 26535115, 2015).
breast carcinoma (1 paper, 2024). "BCL11A, MLLT3, ZNF521, PHC1, and PCGF3 also showed subtype-specific dysregulation in breast cancers; BCL11A, ZNF521, and PHC1 were specifically downregulated in luminal subtype cancers relative to their matched normal tissue." (PMID 39545637, 2024).
lung carcinoma (1 paper, 2021). "In this study, we investigated whether PHC3 like PHC1 plays the same role in regulating lung cancer stem cells." (PMID 34424425, 2021).
psychosis (1 paper, 2019). "Bioinformatic analysis of WES and CGH-array data selected 15 common for psychosis phenotype damaging variants and 6 of them were rare mutations, including paternal 3p26.3-loss and 5 additional missense mutations located in ACSF2, MPRIP, PHC1, PER3, and RERE genes." (PMID 30710087, 2019).
Sepsis (1 paper, 2025). Sepsis is defined as life-threatening organ dysfunction caused by a dysregulated host response to infection. "A total of six hub genes (RORA, L3MBTL2, PHC1, RPA1, CHD3, and RANGAP1) associated with SUMOylation was identified in sepsis in the current study." (PMID 40274894, 2025). "Aflatoxin B1 was identified as a prospective therapeutic agent for sepsis based on CHD3, L3MBTL2, PHC1, RANGAP1, and RORA." (PMID 40274894, 2025). "This study shows that hub genes (RORA, L3MBTL2, PHC1, RPA1, CHD3, and RANGAP1) may distinguish controls and diseases to facilitate diagnosis of sepsis." (PMID 40274894, 2025).
cancer (5 papers, 2011 to 2025). A tumor composed of atypical neoplastic, often pleomorphic cells that invade other tissues. "We found that 30 of these genes which included Nckap1l, Ncf1, Pla2g15, Unc93b1, Lrrc33, Rgs10, Gmfg, Rbm25, C3ar1, Ccdc88b, Fam105a, Gng11, Phc1, Rasa4, Dag1, Tyrobp, Tmsb4x, Cfp, Prkd1, Gp49a, Trem2, C1qc, Lyz2, Igfbp7, Rab30, Cxcl16, Egfl7, Ube2r2, Pltp, and Cfb, showed a relation with cancer." (PMID 32812032, 2020).
tumor (4 papers, 2012 to 2024). "Among these genes, several tumor-related genes such as Gata3, Arnt and Tdgf1, epigenetic associated genes such as PHC1 and Uty were identified." (PMID 22952821, 2012). "Knocking down PHC1 in particular with shPHC1.1 significantly reduced the tumor sizes compared to that of the control." (PMID 33990559, 2021).
neurodevelopmental disorder (2 papers, 2020 to 2022). A behavioral and cognitive disorder with onset during the developmental period that involves impaired or aberrant development of intellectual, motor, or social functions. "Mutations in PRC1 members such as PHC1 and PCGF2 lead to human neurodevelopmental disorders." (PMID 36117635, 2022).
heart disease (1 paper, 2024). "Participants having no heart disease (phc1) or having good SRH (psc4) at baseline were more likely to be successful agers after the 20-year follow-up even after the adjustments for age and gender." (PMID 38824528, 2024).
PHC1 also shares sentences with these, for which no sentence is quoted: infection (4 papers); intellectual disabilities (2); autism spectrum disorder (1); autosomal recessive primary microcephaly (1); cerebral malformation (1); Down syndrome (1); Fanconi anemia (1); Fanconi anemia complementation group A (1); Greig cephalopolysyndactyly syndrome (1); Huntington disease (1); Kabuki syndrome (1); leukemia (1); Pitt-Hopkins syndrome (1); schizophrenia (1); teratoma (1).